PRMT5 (protein arginine methyltransferase 5)
Diseases named in the same sentence as PRMT5 in open-access papers (continued):
Sharing a sentence is not in itself a finding about the gene and the disease.
osteosarcoma (7 papers, 2019 to 2024). A usually aggressive malignant bone-forming mesenchymal neoplasm, predominantly affecting adolescents and young adults. "In osteosarcoma cells, PRMT5 is relocalized in the nucleus by the transcription factor SNAIL and its corepressor AJUBA." (PMID 37458145, 2023). "Three PRMTs (i.e., PRMT1, PRMT4/CARM1 and PRMT5) have each been shown to control vitamin D3-dependent transcription in osteosarcoma cells via interactions with SRC-1/NCOA1, whereas PRMT5 binds to the SWI/SNF component BRG1/SMARCA4 in different cell types." (PMID 37593409, 2023). "We previously observed that the expression of NDRG2 was low in many types of solid cancers, including SAS (oral squamous cell carcinoma) and U2OS (osteosarcoma), and cell proliferation was significantly suppressed by silencing PRMT5 expression with the degradation of AKT and NEMO proteins." (PMID 38474089, 2024). "In agreement with our findings, the publicly available mixed osteosarcoma-Kuijjer dataset also revealed that the high expression level of PRMT5 was correlated with poor metastasis-free survival probability, although the overall survival probability was not significantly different." (PMID 32023548, 2020). "Our findings on the distinct functions of PRMT1, PRMT4/CARM1 and PRMT5 complement and extend previous studies that examined the contribution of PRMTs and their cognate epigenetic modifications in vitamin D3-dependent transcriptional regulation in rat osteosarcoma cells." (PMID 37593409, 2023). "PRMT1, PRMT4/CARM1, PRMT5 and PRMT7 are prevalent isoforms that are functionally expressed in myogenic cells and osteosarcoma cells." (PMID 37593409, 2023). "In this study, a magnetic-driven hydrogel microrobots carried the PRMT5 inhibitor, EPZ015666, which was synthesized to evaluate a precision synthetic lethality nanodrug for osteosarcoma treatment." (PMID 35875497, 2022).
autoimmune disease (6 papers, 2017 to 2024). A disorder resulting from loss of function or tissue destruction of an organ or multiple organs, arising from humoral or cellular immune responses of the individual to their own tissue constituents. "Using conditional KO mice, the authors showed that thymic deficiency of Prmt5 predisposed mice to developing autoimmune diseases while enhancing antitumor efficacy." (PMID 39403925, 2024). "A selective inhibitor of Prmt5 reduces the clinical score of EAE, suggesting the critical role of Prmt5 in autoimmune disease." (PMID 37533053, 2023). "These PRMT5 knockout mice can develop severe scurfy-like autoimmune diseases in mice by showing an impaired number of Treg cells in the spleen, while no change was observed in the Tregs from peripheral lymph nodes." (PMID 37936703, 2023). "Further understanding of upstream PRMT5 regulators and downstream PRMT5 targets in activated Th cells should provide novel and useful therapeutic targets in the treatment of T cell-mediated autoimmune diseases such as MS." (PMID 30941147, 2019). "We conclude that developing a small-molecule inhibitor or other strategies to inhibit the function of PRMT5 might be of therapeutic importance in the management of UC and potentially other autoimmune diseases." (PMID 28588584, 2017). "Controlling T-cell Prmt5 expression may be helpful for the treatment of autoimmune diseases." (PMID 37533053, 2023). "PRMT5 preferentially binds to FOXP3, and a conditional deletion of PRMT5 gene in Tregs leads to deadly scurfy-like autoimmune diseases." (PMID 31681337, 2019).
Autoimmunity (6 papers, 2019 to 2024). The occurrence of an immune reaction against the organism's own cells or tissues. "The current data suggest the potential underlying mechanism driven by PRMT5 as a target of autoimmunity and consequently resulting fibrosis in SSc." (PMID 38684324, 2024). "PRMT5 deletion in Tregs caused scurfy-like symptoms and severe autoimmunity in the mice." (PMID 30800128, 2019). "The transgenic mice that possess PRMT5 deficient Tregs displayed severe scurfy-like autoimmunity." (PMID 30800128, 2019). "Paradoxically, PRMT5 is also required for the suppressive function of regulatory T cells (Treg), which is essential to suppress autoimmunity." (PMID 32743345, 2020). "PRMT5 induction and subsequent Th1 and Th17 differentiation exemplify the pathological roles played by PRMT5 in autoimmune disorders, experimental autoimmune encephalomyelitis (EAE) and acute graft-versus-host diseases (aGVHD)." (PMID 32743345, 2020). "Mice with conditional knock out (cKO) of PRMT5 expression in Tregs develop severe scurfy-like autoimmunity." (PMID 30800128, 2019). "Our results indicate that PRMT5 is indispensable for normal Treg activity, which prevents the severe autoimmunity scurfy-like symptoms." (PMID 30800128, 2019). "Similarly, PRMT5 also plays a crucial role in Tregs suppression, as demonstrated by severe autoimmunity observed in PRMT5 conditional knockout mice." (PMID 39144146, 2024). "PRMT5 inhibitors may be also applicable to diseases where the suppression of uncontrolled T cell activation is desirable, such as seen in autoimmunity." (PMID 32328070, 2020). "Mice with conditional PRMT5 knockout in Treg cells develop severe scurfy-like autoimmunity." (PMID 32743345, 2020). "The inhibition of PRMT5 may provide a novel strategy for the treatment of diseases where uncontrolled T cell activation has a role, such as autoimmunity." (PMID 32328070, 2020). "FOXP3 is dimethylated by PRMT5 (or PRMT1, PRMT6) at R48 and R51, which attenuates the expression of immunosuppressive genes and may lead to autoimmunity." (PMID 37143582, 2023).
head and neck squamous cell carcinoma (6 papers, 2021 to 2025). A squamous cell carcinoma that arises from any of the following anatomic sites: lip and oral cavity, nasal cavity, paranasal sinuses, pharynx, larynx, and salivary glands. "In head and neck squamous cell carcinoma (HNSCC), PRMT5-mediated H3R2me2s facilitates the recruitment of the MLL/SET1/WDR5 complex to the TWIST1 promoter, increasing H3K4me3 and TWIST1 transcription, thereby promoting EMT and lymph node metastasis." (PMID 41204384, 2025). "USP7 and PRMT5-dependent G3BP2 stability drives de novo lipogenesis and tumorigenesis in head and neck squamous cell carcinoma." (PMID 39944823, 2025). "Our findings demonstrate that upregulation of PRMT5 and WDR77 correlates with the poor survival of head and neck squamous cell carcinoma (HNSCC) patients." (PMID 39594744, 2024). "Similarly, in head and neck squamous cell carcinoma (HNSCC), the overexpression of the arginine methyltransferase PRMT5 resulted in increased Twist1 and N-cadherin levels, whilst E-cadherin levels decreased." (PMID 38827317, 2024). "The expression of both PRMT5 and PRMT1 has been tested in multiple head and neck squamous cell carcinoma (HNSCC) and A549 cells where OHKC (immortalized normal oral keratinocytes) and DOK (dysplastic oral keratinocytes) cells serve as normal and dysplastic cell lines." (PMID 38709899, 2024).
mesothelioma (6 papers, 2020 to 2025). A usually malignant and aggressive neoplasm of the mesothelium which is often associated with exposure to asbestos. "PRMT5 inhibitors exerted promising effects on in vitro models of mesothelioma with MTAP deletion, as its inhibition selectively inhibited tumor cell proliferation and downregulated genes related to cell cycle and epithelial–mesenchymal transition." (PMID 40362535, 2025). "In agreement with previous studies underlining the potential value of PRMT5 as a therapeutic approach, our results represent a starting point for the evaluation of PRMT5 inhibitors also in MTAP‐deleted mesothelioma." (PMID 32301278, 2020). "On the other hand, for MTAP deficient mesothelioma, although L-alanosina is not being further investigated, at least one trial is ongoing with a different drug, PRMT5-MTA inhibitor." (PMID 37445594, 2023). "This implies that lower micromole doses are achievable and could be locally administered, achieving localised exposure to mesothelioma at concentrations capable of suppressing PRMT5 expression." (PMID 33795785, 2021). "Emerging molecular targets in mesothelioma include mesothelin (MSLN), oxytocin receptor (OXTR), protein arginine methyltransferase (PRMT5), and carbohydrate sulfotransferase 4 (CHST4)." (PMID 40362535, 2025).
non-Hodgkin lymphoma (6 papers, 2021 to 2026). Distinct from Hodgkin lymphoma both morphologically and biologically, non-Hodgkin lymphoma (NHL) is characterized by the absence of Reed-Sternberg cells, can occur at any age, and usually presents as a localized or generalized lymphadenopathy associated with fever and weight loss. "PRMT5 inhibitor GSK3326595, currently in phase I clinical trial for solid tumors and non-Hodgkin’s lymphoma (NCT02783300; ClinicalTrials.gov), acts by occupying the binding site of substrate peptides in the PRMT5/MEP50 complex and thereby inhibits the enzymatic activity of PRMT5." (PMID 36797243, 2023).
chronic lymphocytic leukemia (5 papers, 2017 to 2023). "In B-cell chronic lymphoid leukemia (CLL) cell lines, the overexpression of PRMT5 is due to its enhanced translation, caused by an alteration of the expression of miR-19a, -25, -32, -92b, and -96, which targets PRMT5." (PMID 36358861, 2022). "However, one study found PRMT5 to be over-expressed in transformed chronic lymphocytic leukemia (B-CLL) cells with elevated levels of global H4R3me2s marks." (PMID 28678843, 2017). "By reconstructing an event of genomic deregulation for PRMT5 in CLL, we validated our strategy to identify deregulated cancer driving factors in a highly cell type specific manner and contributed to further understanding of PRMT5 function in chronic lymphocytic leukemia." (PMID 32555249, 2020).
colorectal tumors (5 papers, 2015 to 2025). "Furthermore, studies have shown that Protein arginine methyltransferase 5 (PRMT5)-deficient mouse B cells exhibit dysregulated distribution of RNA m6A modifications, which slows colorectal tumor progression." (PMID 39987091, 2025). "We found that PRMT5 expression was higher in colorectal tumors than the adjacent normal counterparts." (PMID 36474242, 2022). "We next investigated whether si-PRMT5 inhibits the growth of colorectal tumor xenografts in nude mice." (PMID 26078354, 2015).
Fanconi anemia (5 papers, 2016 to 2026). Fanconi anemia (FA) is a hereditary DNA repair disorder characterized by progressive pancytopenia with bone marrow failure, variable congenital malformations and predisposition to develop hematological or solid tumors. "The most studied type II PRMT, PRMT5, has pro-proliferative and pro-oncogenic roles even though it appears to have the opposite effect in Fanconi anemia patients." (PMID 29568320, 2018). "Mechanistically, we identify PRMT5 as a major regulator of DNA damage response (DDR) gene splicing in BCSCs, particularly those integral to the Fanconi Anaemia and homologous recombination pathways, with PRMT5 inhibition synergising with chemotherapy to promote BCSC apoptosis." (PMID 39695328, 2025). "This suggested that the Fanconi Anemia pathway plays a role in TE repression in early PGCs, likely through a mechanism involving the promotion of repressive H2A/H4R3me2s marks on TEs by FANCD2 and the acceleration of this process by Prmt5." (PMID 37566603, 2023).
Infertility (5 papers, 2021 to 2024). "PRMT5 acts as a crucial factor for the survival of mouse primordial germ cells, maintenance of spermatogonial stem cells, and in the progression of spermatogenesis as germ cell-specific PRMT5 deletion with Stra-Cre resulting in infertility in male mice." (PMID 34360715, 2021). "Our results indicate that promotion of PRMT5 may provide novel therapeutic strategies for the treatment of decidualization defects in infertile women, such as those with endometriosis." (PMID 36195592, 2022).
metastatic tumors (5 papers, 2013 to 2026). "The addition of a PRMT5 pharmacologic inhibitor to Gem and Ptx therapy resulted in a lower final tumor weight and fewer metastatic tumors." (PMID 40723820, 2025). "As a positive regulator of the E2F1 axis, this information endorses PRMT5 as a viable therapeutic target and further suggests drugs targeting PRMT5 will find clinical utility in metastatic disease." (PMID 32709847, 2020). "The distribution of cytoplasmic PRMT5 protein differs significantly among normal epidermis, benign nevi, and malignant and metastatic tumors." (PMID 24098663, 2013). "Despite this heterogeneity, the percentage of nuclear PRMT5+ cells was significantly lower in metastatic tumors compared to primary cutaneous tumors (p<0.0001)." (PMID 24098663, 2013). "Our observations that PRMT5 was predominantly localized in the cytoplasm of cell lines were consistent with data showing higher cytoplasmic expression in metastatic tumors." (PMID 24098663, 2013). "The distribution of nuclear PRMT5 protein differs significantly among normal epidermis, benign nevi, and malignant and metastatic tumors." (PMID 24098663, 2013). "Until now, three PRMT5 inhibitors (GSK3326595, JNJ-64619178 and PF-06939999) are being used in six clinical trials (NCT02783300, NCT03573310, NCT03614728, NCT03854227, NCT04555473, NCT04676516) for the therapy of hematologic and solid tumors, containing primary and metastatic tumors." (PMID 34522232, 2021).
pancreatic adenocarcinoma (5 papers, 2019 to 2023). "PRMT5 expression in pancreas adenocarcinoma ductal was higher than that in pancreas adenocarcinoma other subtype and pancreas colloid (mucinous non‐cystic) carcinoma." (PMID 31851779, 2020). "First, by using quantitative real-time PCR and a paired t-test statistical analysis, we demonstrated that PRMT5 expression was higher in pancreatic adenocarcinoma (PDAC) tumor samples than in adjacent samples." (PMID 30922330, 2019).
pancreatic ductal adenocarcinoma (5 papers, 2022 to 2026). An infiltrating adenocarcinoma that arises from the epithelial cells of the pancreas. "The oncogenic role and underlying mechanism of PRMT5 in pancreatic ductal adenocarcinoma (PAAD) remained to be elucidated." (PMID 40384988, 2025). "PRMT5 as an anti-cancer target has gained significant interest in recent years and high levels of PRMT5 protein are associated with worse survival outcomes across multiple cancer types, including pancreatic ductal adenocarcinoma (PDAC)." (PMID 36765032, 2023). "For example, the transcription regulator PRMT5 (protein arginine methyltransferase 5) was identified as a potential gene target in combination with gemcitabine for pancreatic ductal adenocarcinoma." (PMID 35740503, 2022).
rheumatoid arthritis (5 papers, 2017 to 2025). A chronic, systemic autoimmune disorder characterized by inflammation in the synovial membranes and articular surfaces. "The present study aimed to to explore the association between anti-PRMT5 antibodies and rheumatoid arthritis (RA)." (PMID 40790333, 2025). "Prmt5 also regulates the E2F pathway, enhances cancer cell migration and invasion, and modulates fibroblast-like synoviocytes in rheumatoid arthritis." (PMID 37533053, 2023). "Thus, inhibition of PRMT5 might be a potential therapeutic agent to attenuate pathological progression in rheumatoid arthritis." (PMID 27860244, 2017).
acute lymphoblastic leukemia (4 papers, 2019 to 2024). Leukemia with an acute onset, characterized by the presence of lymphoblasts in the bone marrow and the peripheral blood. "In acute lymphoblastic leukemia (ALL), PRMT5 promotes the proliferation of lymphocytes by inhibiting apoptosis, and the down-regulation of H4R3sme2 by PRMT5 silencing induced ALL differentiation from the pre-B to immature B stage." (PMID 34513846, 2021).
anemia (4 papers, 2018 to 2025). A reduction in the number of red blood cells, the amount of hemoglobin, and/or the volume of packed red blood cells. "When fetal liver cells lack PRMT5, the outcome is embryonic mortality because the genes that encode DNA methyltransferase 3A and 3B are overexpressed in PRMT5-null embryos, causing severe anemia." (PMID 39584923, 2024). "PRMT5 plays an essential role in blood progenitor cell specification as demonstrated by the anemia and pancytopenia developed by conditional ablation of PRMT5 (Mx1-Cre) in adult hematopoietic stem cells (HSC)." (PMID 30613353, 2018).
astrocytomas (4 papers, 2015 to 2025). "IDH-mutant WHO grade-4 astrocytomas that cause excessive production of 2-HG may also alter 2-OG-dependent dioxygenase enzymes, eventually leading to PRMT5 inhibition." (PMID 38827324, 2024). "Statistically significant differences in PFS were observed among all G4 astrocytomas that expressed PRMT5 and received either TMZ or TMZ plus other chemotherapies, regardless of their IDH or MGMT-promoter methylation status (p-value = 0.0014)." (PMID 38827324, 2024). "In our current study, we have observed that there were significant differences in PFS of all G4 astrocytoma with upregulated PRMT5, receiving TMZ or TMZ plus other chemotherapeutic agents, regardless of IDH or MGMT-promoter status." (PMID 38827324, 2024). "PRMT5 is usually lowly expressed in control brain tissue and glial cells of low‐grade astrocytomas, while it is highly expressed in GBMs." (PMID 39711357, 2024). "Our current research provides a clear example, where 50% (n = 11/22) of IDH-mutant G4 astrocytoma showed upregulated PRMT5 expression, and 10 of them had unmethylated MGMT-promoter." (PMID 38827324, 2024). "IDH-mutant WHO-G4 astrocytomas with upregulated PRMT5 and methylated MGMT-promoter who received only TMZ (n = 8) had the longest PFS." (PMID 38827324, 2024). "Notably, IDH-mutant astrocytomas exhibiting both MGMTp methylation and elevated PRMT5 expression show significantly prolonged PFS with TMZ monotherapy compared to other subgroups." (PMID 41346390, 2025). "Statistically significant differences in progression-free survival (PFS) were also observed among all G4 astrocytomas that expressed PRMT5 and received either temozolomide (TMZ) or TMZ plus other chemotherapies, regardless of their IDH or MGMT-methylation status (p-value=0.0014)." (PMID 38827324, 2024). "There is no clear evidence on whether IDH mutation or MGMT promoter methylation can affect the anti-tumor activity of PRMT5 in G4 astrocytoma when used in conjunction with other chemotherapeutic agents." (PMID 38827324, 2024). "Furthermore, MGMT methylation in IDH-mutant astrocytomas may interact with other epigenetic modifiers, particularly PRMT5, to modulate tumor progression and therapeutic response." (PMID 41346390, 2025). "The higher the grade, the more aggressive the astrocytoma with wildtype IDH, and the more significant the upregulation of PRMT5." (PMID 38827324, 2024). "Additionally, we hypothesize that the efficacy of TMZ in G4 astrocytoma may improve with the use of PRMT5 inhibitors, irrespective of the methylation status of MGMT-promoter or IDH mutational status." (PMID 38827324, 2024).